KMT2C (lysine methyltransferase 2C)
Diseases named in the same sentence as KMT2C in open-access papers (continued):
Sharing a sentence is not in itself a finding about the gene and the disease.
ovarian carcinoma (9 papers, 2015 to 2024). A malignant neoplasm originating from the surface ovarian epithelium. "The KMT2C gene has mutations or deletions in many tumors, including leukemia, liver cancer, pancreatic cancer, gastric cancer, cholangiocarcinoma, ovarian cancer, and bladder transitional cell carcinoma." (PMID 32943985, 2020). "XIST affects the expression of KMT2C in ovarian cancer by enhancing the stability of KMT2C mRNA through the direct targeting of mi -93-5p." (PMID 39165358, 2024). "Recurrently mutated ovarian cancer driver genes, including LRP1B, KMT2A, ARID1A, KMT2C and ATRX were also found in two cell lines." (PMID 37525498, 2023). "The study found that XIST can affect the expression of KMT2C in the ovarian cancer via targeting miR-93-5p." (PMID 32943985, 2020). "Overexpression of KMT2C inhibited XIST silencing-induced proliferation of cancer stem cells, and KMT2C was able to mediate paclitaxel resistance induced by XIST in ovarian cancer." (PMID 32943985, 2020). "The results of this study suggest that the miR-93-5p/XIST/KMT2C signaling axis may provide new potential therapeutic targets for ovarian cancer treatment and play an important role in future ovarian cancer therapy." (PMID 39165358, 2024). "The results of this study suggested that miR-93-5p/XIST/ KMT2C signal axis can provide new potential therapeutic target and may play an important role in the treatment of ovarian cancer in the future." (PMID 32943985, 2020). "Overexpression of XIST can enhance the anti-cancer sensitivity of paclitaxel to ovarian cancer cells, and its effect may be related to the up-regulation of KMT2C." (PMID 32943985, 2020). "Thus, we can conclude that the regulation effect of XIST in Ovarian cancer stem cells and paclitaxel resistance depend on KMT2C." (PMID 32943985, 2020). "In ovarian cancer, XIST promotes the stability of lysine (K)-specific methyltransferase 2C (KMT2C) mRNA, thereby indirectly promoting histone H3 methylation at lysine 4 and hence decreasing CSC proliferation." (PMID 33799834, 2021). "Finally, to determine if the genes that display altered mRNA expression levels in ovarian cancer patient samples (PIK3CA, TTN, RYR2, KMT2C, KRAS, PTEN, and ARID1A) have any clinical value, we checked the effect of their expression on recurrence and survival of patients with ovarian cancer." (PMID 32626534, 2020).
breast tumors (8 papers, 2015 to 2023). "In addition, KMT2C is the gene with the highest mutation count predominantly found in BC, with some mutations associated with chromatin function, affecting transcription mechanisms identified in breast tumor development." (PMID 35589867, 2022). "H3K4 methyltransferase KMT2C/MLL3 is mutated in several solid malignancies, including more than 10% of breast tumours." (PMID 36933062, 2023). "Despite the recent interest in KMT2C, its role in breast tumour initiation, progression and response to therapy remains poorly understood." (PMID 36933062, 2023).
Kleefstra syndrome 2 (8 papers, 2022 to 2025). "Of note, 3 of the 21 patients following segregation analysis were detected with missense variants in the KMT2C gene (Kleefstra syndrome 2; OMIM#617,768) which were inherited from a healthy parent." (PMID 37543562, 2023). "Recent studies in humans have identified mutations in KMT2C, an enzyme responsible for modifying histone tails and depositing H3K4me1 and H3K4me3, as being associated with Kleefstra syndrome 2 and autism spectrum disorder (ASD)." (PMID 37538398, 2023). "These phenotypic changes are relevant to the human conditions of ASD and Kleefstra Syndrome 2, both of which are associated with neurodevelopmental disorders that can be attributed to the loss of function of KMT2C." (PMID 37538398, 2023). "Our findings shed light on the involvement of KMT2C in neurodevelopmental processes and establish a valuable model for elucidating the cellular and molecular mechanisms underlying KMT2C mutations and their relationship to Kleefstra syndrome 2 and ASD." (PMID 37538398, 2023). "KMT2C (histone lysine N-methyltransferase 2C, also known as MML3, myeloid/lymphoid or mixed-lineage leukemia 3) is a causal gene for Kleefstra syndrome 2, a rare neurodevelopmental disorder." (PMID 41301465, 2025). "Human KMT2C, MADD and TCF4 are causative genes for three neurodevelopmental disorders, Kleefstra syndrome 2, DEEAH syndrome and Pitt-Hopkins syndrome, respectively." (PMID 37294900, 2024). "A 7q36.1q36.2 deletion containing several pathogenic genes, including DPP6, KMT2C, ASB10, PRKAG2, KCNH2, among which KMT2C is a causative gene for Kleefstra syndrome 2 (MIM#617768)." (PMID 37892645, 2023). "In humans, loss-of-function mutations in KMT2C have been associated to the appearance of ASD-like behaviors and Kleefstra syndrome 2, however limited information is available about the phenotype." (PMID 37538398, 2023). "KMT2C (histone lysine N-methyltransferase 2C, also known as MML3, myeloid/lymphoid or mixed-lineage leukemia 3) located on human chromosomal band 7q36.1, is a causal gene for Kleefstra syndrome 2 (a rare neurodevelopmental disorder) and a risk gene for ASD." (PMID 41301465, 2025).
lung cancer (8 papers, 2021 to 2025). A malignant neoplasm involving the lung. "Mutations also occur in chromatin-modifying genes, such as ARID1A, ARID2, SETD2, SMARCA4 and MLL3 (KMT2C), leading to epigenomic abnormalities that overlap with genomic alterations, further complicating lung cancer biology." (PMID 40849356, 2025).
myeloid leukemia (8 papers, 2015 to 2025). A clonal proliferation of myeloid cells and their precursors in the bone marrow, peripheral blood, and spleen. "Mutated MLL3 (or KMT2C) proteins have been implicated in multiple cancers, including urothelial carcinoma, human lymphoid, and myeloid leukemia." (PMID 34071259, 2021).
cervical carcinoma (7 papers, 2017 to 2025). A carcinoma arising from either the exocervical squamous epithelium or the endocervical glandular epithelium. "The most frequent significantly mutated genes (SMGs) across the 430 cervical carcinomas were previously reported and included PIK3CA (27%), KMT2C (also known as MLL3) (19%), KMT2D (also known as MLL2) (13%), EP300 (12%), FBXW7 (12%), FAT1 (8%), and PTEN (8%)." (PMID 34620846, 2021). "KMT2C and LRP1B gene mutations are independent predictors of TMB-high status in cervical cancer." (PMID 36333792, 2022). "We also showed that cervical cancers with mutations in the KMT2C and LRP1B genes have an increased TMB, and our data indicate that KMT2C and LRP1B gene mutations may serve as biomarkers to forecast therapeutic reactions." (PMID 36333792, 2022).
melanoma (7 papers, 2020 to 2026). A malignant, usually aggressive tumor composed of atypical, neoplastic melanocytes. "Lastly, B melanoma antigen 1 (BAGE1) was generated by juxta-centromeric reshuffling of the KMT2C/MLL3 gene; while its function remains unknown, it is an antigen found in human melanomas." (PMID 41347230, 2025).
metastatic tumors (7 papers, 2016 to 2024). "However, mutations in genes such as BRCA2, ARID1A and KMT2C were reported only in metastatic tumors, implying evidence of their contribution to disease progression." (PMID 39594781, 2024). "Here, we describe for the first time that loss of the KMT2C methyltransferase domain accelerates tumour growth and promotes a switch from indolent to lethal, metastatic disease in vivo when combined with other PCa associated mutational events, specifically loss of PTEN." (PMID 35354467, 2022). "Apart from ARID1A and KMT2C, ZFHX3 and NF1 are also associated with endocrine resistance in metastatic disease." (PMID 39594781, 2024). "To gain insight into the mutational spectrum of human PCa we analysed a cohort of 1013 patients with either localized or metastatic disease (MSKCC/DFCI cohort) and found KMT2C to be the 7th most frequently mutated gene." (PMID 35354467, 2022).
myelodysplastic syndrome (7 papers, 2019 to 2024). A clonal hematopoietic disorder characterized by dysplasia and ineffective hematopoiesis in one or more of the hematopoietic cell lines. "Other studies suggest that loss of KMT2C may contribute to the development of myelodysplastic syndromes and acute myelocytic leukemia (AML) by promoting myelopoiesis." (PMID 39165358, 2024). "The second highly expressed transcript is Kmt2c (lysine methyltransferase 2C), which is a tumour suppressor mutated or deleted in the peripheral T-cell lymphoma and myelodysplastic syndrome (MDS)." (PMID 36590595, 2022). "In the complex genome of a case (BNGOHM-0000191) with myelodysplastic syndromes (MDS), OGM detected a 392.8 kbp tandem duplication on chr7, resulting in the duplication of KMT2C, GALNTT11, and GALNT5." (PMID 38137484, 2023). "In contrast, MLL3 (KMT2C), which is frequently lost in myelodysplastic syndrome (MDS), AML, aggressive nasopharyngeal carcinoma, and CRC, acts as a myeloma inhibitor that suppresses the self-renewal of hematopoietic stem cells and engages in differentiation via IL-1 stimulation." (PMID 37394580, 2023).
autism (6 papers, 2015 to 2023). Persistent deficits in social interaction and communication and interaction as well as a markedly restricted repertoire of activity and interest as well as repetitive patterns of behavior. "We found differential expression of autism-relevant genes in our DE gene list that are also associated with cell adhesion (Dscam, Reln) or gene regulation (Kat2b, Kmt2c, Med13/Med13l, Tbl1xr1, Ubn2)." (PMID 33757588, 2021). "Another autism related protein, the histone methyltransferase KMT2C was found to be reduced in the hippocampal synapse of male mice." (PMID 32012899, 2020). "KMT2C (lysine methyltransferase 2C) is an autism candidate gene and downstream target gene of AR." (PMID 36803626, 2023).
esophageal squamous cell carcinoma (6 papers, 2016 to 2024). Esophageal squamous cell carcinoma (ESCC) is a type of esophageal carcinoma (EC) that can affect any part of the esophagus, but is usually located in the upper or middle third. "As a histone modifier, KMT2C also frequently mutates in esophageal squamous cell carcinoma." (PMID 38912415, 2024). "KMT2C is frequently altered in many types of cancer, including liver cancer, cutaneous squamous cell carcinoma, and esophageal squamous cell cancer." (PMID 27023146, 2016).
autism spectrum disorder (5 papers, 2017 to 2024). A spectrum of developmental disorders that includes autism, and Asperger syndrome. "In summary, our study has revealed the involvement of four known genes (DEAF1, CLCN3, KMT2C, and DHX30) as well as two novel genes (TRPC4 and SCFD2) in autism spectrum disorder across six families from Qatar." (PMID 38025430, 2023).
endometrial cancer (5 papers, 2018 to 2023). Primary or metastatic malignant neoplasm involving the endometrium (mucous membrane that lines the endometrial cavity). "Mutations in the KMT2C gene have been found in gastric, CRC, and endometrial cancer, indicating its role in tumor development." (PMID 38023196, 2023).
osteosarcoma (5 papers, 2017 to 2023). A usually aggressive malignant bone-forming mesenchymal neoplasm, predominantly affecting adolescents and young adults. "The cytoplasmic localization of KMT2C could likely lead to a loss, gain, or change in its function supporting osteosarcoma tumorigenesis." (PMID 30093974, 2018). "We evaluated the KMT2C immunohistochemical expression of 32 samples on Tissue MicroArray (TMA) sections and we observed that all osteosarcoma samples showed cytoplasmic expression of KMT2C and 31/32 (97%) osteosarcoma samples also showed nuclear localization." (PMID 30093974, 2018). "We found that most of analysed osteosarcoma samples (97%) showed both nuclear and cytoplasmic immunohistochemical expression of KMT2C and the percentage of cytoplasmic positive cells was higher than the percentage of nuclear positive cells." (PMID 30093974, 2018). "The aim of this study was to understand the role of KMT2C in the osteosarcoma carcinogenesis and metastatic progression to identify a new molecular target and to provide new therapeutic approach." (PMID 30093974, 2018). "We observed that KMT2C was up-regulated and down-regulated in 84.4% (27/32) and 15.6% (5/32) of osteosarcoma samples respectively compared to osteoporosis tissue sample used as control." (PMID 30093974, 2018). "Our hypothesis is that KMT2C affecting negatively or positively the enhancer activity of genes involved in osteosarcoma progression, it could play a role of oncogene or oncosuppressor, particularly in the degradation and attachment of tumor cells to ECM." (PMID 30093974, 2018). "In conclusion, we obtained valuable information about KMT2C in osteosarcoma: we found a nuclear-cytoplasmic trafficking that could have a role in osteosarcoma carcinogenesis and progression probably linked to the consequent change of its function." (PMID 30093974, 2018). "Therefore, the aim of this study was to confirm the role of KMT2C in the osteosarcoma carcinogenesis on a large cohort of osteosarcoma samples and evaluate it in osteosarcoma metastatic progression on osteosarcoma cell lines." (PMID 30093974, 2018). "However, further studies are needed to better understand the role of KMT2C in osteosarcoma carcinogenesis and progression because epigenetic therapy is promising for cancer treatment in the light of recent developments in this field." (PMID 30093974, 2018). "Given that the mechanism by which SERPINE1 promotes the invasion and metastasis of osteosarcoma cells remains unknown, following our analysis, we hypothesize a role of KMT2C in this process." (PMID 30093974, 2018). "The cytoplasmic localization of KMT2C could lead to a change in its function supporting osteosarcoma carcinogenesis and progression." (PMID 30093974, 2018). "KMT2C is mutated in a wide spectrum of neoplasms, it has been linked to tumorigenesis, it has never been studied in osteosarcoma and its role in metastatic progression is unknown." (PMID 30093974, 2018). "Our earlier data showed that KMT2C could be involved in osteosarcoma carcinogenesis." (PMID 30093974, 2018). "KMT2C showed the highest number of variations; it is an important component of a histone H3 lysine 4 methyltransferase complex and it is one of the histone modifiers previously implicated in carcinogenesis, never studied in osteosarcoma." (PMID 29113313, 2017). "Therefore, our hypothesis is that KMT2C could be involved in osteosarcoma carcinogenesis too." (PMID 29113313, 2017). "Although not previously reported in osteosarcomas, mutations in KMT2B/MLL2, KMT2C/MLL3, or KMT2D/MLL4 that catalyze mono‐ or di‐methylation of H3K4 are frequently observed in many types of cancer." (PMID 35920001, 2022). "KMT2C is a chromatin-modifying and remodelling protein and its expression has never been studied in osteosarcoma." (PMID 30093974, 2018).
osteosarcoma (continued). "Our data highlighted that α-CATENIN is expressed in osteosarcoma cell lines and we could argue that α-CATENIN expression values could decrease only during metastasis development in osteosarcoma and that this process could be regulated by KMT2C." (PMID 30093974, 2018). "Therefore, our study shows that KMT2C could be involved in ECM modifications that lead to metastatic progression and it could regulate the MMP2 activity in osteosarcoma progression." (PMID 30093974, 2018).
schizophrenia (5 papers, 2018 to 2025). A major psychotic disorder characterized by abnormalities in the perception or expression of reality. "In addition to including members of the Set1-like H3K4 methyltransferase family (Kmt2a, Kmt2b, Kmt2c, and Kmt2d), these modules also encompassed rare variant genes associated with schizophrenia and ASD (Setd1a, Cacna1g, Ank3, Shank1, and Shank3)." (PMID 40102613, 2025). "Recently, novel or de novo pathogenic variants in the KMT2C gene have been reported to cause a variety of developmental abnormalities, including ID, ASD, schizophrenia, and non-syndromic primary tooth eruption failure." (PMID 38356881, 2024). "A comparison of gene expression patterns between patients with schizophrenia and controls showed that the expression level of KMT2C in postmortem brain tissues was significantly upregulated in schizophrenia patients." (PMID 29341862, 2018).
skin cancer (5 papers, 2017 to 2022). "Furthermore, our analyses uncovered several recurring UV mutations following acute UVB radiation affecting multiple genes including HRNR, TRIOBP, KCNJ12, and KMT2C, which are frequently mutated in skin cancers, indicating their potential role as founding mutations in UV-induced skin tumorigenesis." (PMID 32188867, 2020).
glioma (4 papers, 2015 to 2026). A benign or malignant brain and spinal cord tumor that arises from glial cells (astrocytes, oligodendrocytes, ependymal cells). "Alterations of EZH2, KMT2C, and CHD4 at the genetic or protein level could perturb an epigenetic program, leading to malignant transformation in glioma." (PMID 34996478, 2022).
liver cancer (4 papers, 2016 to 2024). An epithelial or non-epithelial malignant neoplasm that arises from the liver. "In support of this, GFP-linked Kmt2c shRNAs efficiently cooperated with Myc overexpression to drive liver cancer, producing tumors with 50–80% reduction in Kmt2c mRNA expression." (PMID 37261974, 2023).
lymphoma (4 papers, 2022 to 2025). A malignant (clonal) proliferation of B- lymphocytes or T- lymphocytes which involves the lymph nodes, bone marrow and/or extranodal sites. "WES revealed significantly mutated genes, including several known (NCF1, MMP9, and VDR) and possibly other candidate (CNN2, MUC4, MTSS2, KMT2C, HAVCR2, and TCF19) genes, most of which were associated with the physiological activation of lymphoma cells." (PMID 41296384, 2025).
pancreatic ductal adenocarcinoma (4 papers, 2016 to 2021). An infiltrating adenocarcinoma that arises from the epithelial cells of the pancreas. "Decreased expression of KMT2C was associated with attenuated cell proliferation in pancreatic ductal adenocarcinoma and poor outcome in breast cancer." (PMID 29728583, 2018).
adenoma (3 papers, 2015 to 2024). A neoplasm arising from the epithelium.
bladder tumor (3 papers, 2018 to 2023).
Cirrhosis (3 papers, 2014 to 2023). A chronic disorder of the liver in which liver tissue becomes scarred and is partially replaced by regenerative nodules and fibrotic tissue resulting in loss of liver function.
epilepsy (3 papers, 2021 to 2026). A brain disorder characterized by episodes of abnormally increased neuronal discharge resulting in transient episodes of sensory or motor neurological dysfunction, or psychic dysfunction. "Four genes (APOL4, KMT2C, SON, VDR) overlapped a clinical epilepsy panel, supporting the capacity of WGS to recover clinically relevant loci." (PMID 42192833, 2026).
head and neck cancer (3 papers, 2022 to 2024). A primary or metastatic malignant neoplasm affecting the head and neck. "KMT2C, which encodes an lysine methyltransferase, is frequently mutated in various human cancers, including bladder, lung, breast, endometrial, and head and neck cancers." (PMID 38883170, 2024).